MAPT-IT1 (MAPT intronic transcript 1)
Gene: Long non-coding RNA gene on chromosome 17 (45,895,783 to 45,898,798, forward strand). Ensembl gene ENSG00000279685.
Diseases named in the same sentence as MAPT-IT1 in open-access papers:
MAPT-IT1 is named in the same sentence as 2 diseases in open-access papers, as found by Europe PMC text mining. Sharing a sentence is not in itself a finding about the gene and the disease. The quoted sentences say what the papers report.
breast carcinoma (1 paper, 2023). "MAPT-IT1 was up-regulated in breast cancer, and up-regulated in CAVD in this work, but its mechanism is still unknown." (PMID 37491214, 2023).
breast tumor (1 paper, 2024). "C60rf99, LINC01614, AC004585, MAPT-IT1, and AC004585.1 exhibited significantly higher expression levels in breast tumor tissues than in paired or unpaired normal breast tissues (P < 0.05)." (PMID 38189818, 2024). "Additionally, quantitative reverse transcription-polymerase chain reaction (qRT-PCR) analysis revealed that the expression levels of C60rf99, LINC02613, AL133467.1, MAPT-IT1, and AC004585.1 were downregulated in breast tumor tissues relative to normal breast tissues (P < 0.05)." (PMID 38189818, 2024).